TNF (tumor necrosis factor)
Diseases named in the same sentence as TNF in open-access papers (continued):
Sharing a sentence is not in itself a finding about the gene and the disease.
immune dysfunction (continued). "The use of TNF-α in the treatment of immune disorders has gained attention in recent years." (PMID 37630377, 2023). "The abnormal expression of inflammatory factors such as TNF-α, IL-1β, IL-6 and IL-17 might affect the pathophysiological processes such as intestinal flora imbalance and immune dysfunction in DC patients." (PMID 36998438, 2023). "Directly arising from this work, we now identify SAR441566 as a small molecule TNF inhibitor that has the preclinical attributes to become a first in class oral drug with the potential to transform the lives of patients living with multiple TNF driven immune diseases." (PMID 36467083, 2022). "Thus far, we have used TNF-antagonists and other immunosuppressants to mitigate inflammation in auto-immune diseases such as RA and IBD." (PMID 35056521, 2021). "TNF-α, IL-1, IL-6, IL-8, and IL-10 can be secreted from monocytes/macrophages, whereby inflammatory cascade activation plays a major role in the development of immune dysfunction and multiple organ dysfunction following polytrauma." (PMID 34876907, 2021). "Interestingly, inflammatory mediators such as CRP, TNF-α, IL-1ra, IL-6, IL-8, and IL-10 have been identified to be part of both: age-related diseases and trauma-induced immune dysfunction." (PMID 32258173, 2020). "The best way to measure immune dysfunction is unknown, but some studies suggest that TNF-α levels in lipopolysaccharide (LPS)-stimulated whole blood are more accurate in predicting patient outcomes than using HLA-DR expression." (PMID 32936371, 2020). "Anti-TNFα are used widely in auto-immune diseases and have been scarcely proposed in PIMS." (PMID 33344389, 2020). "Once LPS is released into the blood system, it can trigger monocytes and phagocytic cells to secrete large amounts of various pro-inflammatory cytokines such as TNF-α, IL-6, IL-1β and various others that contribute to the pathophysiology of septic shock and other immune diseases." (PMID 30065898, 2018). "Moreover, the stimulated macrophages produce large amounts of inflammatory cytokines, including TNF-α, IL-1β and IL-6, and TNF-α, which evoke the production of other inflammatory cytokines and leads to multiple immune disorders and pain." (PMID 29391009, 2018). "As for TNFβ which has an immunomodulator function and carries a predisposition to various immune diseases that frequently accompany mood disturbance, TNFB∗G of the first intron TNFB +252A/G polymorphism seems also to be associated with high TNFα and TNFβproduction." (PMID 30627222, 2018). "Previous studies suggested that CD is a T helper 1-mediated immune disease characterized by increased cytokine levels of IFN-γ, TNF-α, and IL-12, whereas UC is a T helper 2-mediated immune disease characterized by increased cytokine levels of IL-6 and/or reduced IL-10." (PMID 28683149, 2017). "This experimental setup was aimed to mimic in part the in vivo state, where the immune system cells are likely to encounter IFN-β while in the activated state, induced by inflammation or viral exposure, and characterized by elevated TNF-α, as reported for several immune diseases." (PMID 23626809, 2013). "Additionally, multiplex cytokine analysis revealed significant elevations in Eotaxin, IL-1β, IL-4, IL-6, IL-8, MIP-1α, and TNF-α in SZ patients, whereas IFN-γ, IL-9, IL-1ra, IL-13, MCP-1, MIP-1β, and RANTES were reduced (p < 0.05), indicating a complex immune dysfunction associated with SZ." (PMID 40761785, 2025). "Proinflammatory biomarkers, including tumor necrosis factor-α (TNF-α) may be useful for monitoring post-burn inflammation and/or immune dysfunction, and Thus, it is imaginable that the evaluation these cytokines may serve as a predictive measure of inflammatory homeostasis in burn injuries." (PMID 39576805, 2024). "Therefore, successful treatment of TB requires close monitoring of patients who have received drugs that may affect TNF-related immune dysfunction." (PMID 37035321, 2023).
immune dysfunction (continued). "Antibiotics induced immune dysfunction resulted in disproportionate release of cytokines and increased intestinal mucosal inflammation, including higher expression levels of IL-1β, IL-6, and TNF-α, which were considered as common biomarkers in various inflammatory conditions." (PMID 36726819, 2022). "CTLA4, a negative regulator in auto-immune diseases, participates in the pathways of CAMs and T cell receptor signalling contributing to autoimmune tissue destruction and it might exert a down-regulatory effect on TNF-α, TGF-β, IL1-β and IL16 production." (PMID 29401671, 2018). "Both the dysfunction of MSCs and the overproduction of TNF-α may lead to immune disorders." (PMID 28182106, 2017). "The simultaneous overexpression of TNF-α and IL-6 in PPT-exposed rats indicates immune system disorder and severe damage in lung tissue." (PMID 40277406, 2025). "Research indicates that TNF-α in IBS-D patients exacerbates intestinal inflammation and immune dysfunction, worsening symptoms and increasing risks of mucosal damage and disease recurrence." (PMID 40895313, 2025). "Cytokine profiling showed decreased levels of IL-2, IL-6, IL-10, TNF-α, and IFN-γ, indicating broad-spectrum immune dysfunction." (PMID 40806124, 2025). "These ATMs promote systemic inflammation by increasing the production of cytokines such as tumor necrosis factor-alpha (TNF-α) and interleukin 6 (IL-6), thereby maintaining a vicious cycle of immune dysfunction." (PMID 40564149, 2025). "Dysregulation of the cytokine network further supports the immune dysfunction in ME/CFS, with elevated levels of TNF-α and IL-1β observed in ME/CFS patients." (PMID 39845969, 2024). "The immune dysfunctions of SSc patients are manifested by excessive production of proinflammatory cytokines IL-1, IL-6, IL-17, IFN-α, and TNF-α, which can elicit potent tissue inflammation followed by tissue fibrosis." (PMID 34943909, 2021). "The increased abundance of inflammation-related microbiota resulted in immune disorders and intestinal barrier dysfunction by upregulating TLR2/4/5 and promoting the release of IL-1β and TNF-α." (PMID 33329010, 2020). "There is no definitive evidence that specific cytotoxic drugs, low-dose methotrexate for auto-immune disease, NSAIDs, JAK kinase inhibitors or anti-TNFα agents are contraindicated." (PMID 32256705, 2020). "Both endogenous and exogenous IL-37 have been shown to ameliorate inflammation and regulate immune disorder via inhibiting the production of inflammatory mediators including IFN-γ, TNF-α, IL-6, and IL-18." (PMID 28781417, 2017). "UC is classified as a TH2 type immune disease with an upregulation of interleukin (IL)-5 while CD is considered as TH1 type characterized by high levels of interferon gamma (IFN-γ), IL-12, and tumor necrosis factor alpha (TNF-α)." (PMID 40008255, 2025). "Biomarkers such as C-reactive protein (CRP), interleukin-6 (IL-6), and tumor necrosis factor-alpha (TNF-α) have been shown to correlate with systemic inflammation and immune dysfunction, which may play a role in the development of GI side effects." (PMID 39860995, 2025). "In addition, studies have found that the levels of cytokines (such as tumor necrosis factor alpha, interleukin, etc.)in the serum of GLM patients are significantly elevated, further supporting the correlation between immune dysfunction and the disease." (PMID 41001015, 2025). "Multiple drugs for treating auto-immune disease are focused on primarily blocking IFN-I or TNFα (e.g., with Janus kinase inhibitors (JAKi) and anti-TNFα antibodies), which might lead to undesired up-/dysregulation of the untargeted one." (PMID 38596672, 2024). "Here we have discussed the findings collectively and revealed a clear pattern of evidence of CM improving physiological effects of inflammatory diseases, oxidative stress and immune system disorders by increased GSH, SOD, GPx, TAC and CAT levels and reduced TNF-α, IL-17 and TGF-β." (PMID 35493477, 2022).
immune dysfunction (continued). "In our study, immune dysfunction in the model rats, including the downregulation of the CD4/CD8 ratio, decreased in CD4+CD25+FOXP3+ Tregs and the secretion of inflammatory factors TNF-α and IFN-γ increased, which reflected a negative regulation of haematopoiesis." (PMID 35434141, 2022). "UC is a TH2 type immune disease, with up-regulation of IL-5, whereas CD is a TH1 type immune disease, showing high levels of interferon gamma (IFN-), IL-12, and tumor necrosis factor alpha (TNF-α)." (PMID 32851982, 2021). "Chronic inflammation is due to uncontrolled infiltration by inflammatory and immune cells, and the release of pro-inflammatory mediators such as tumor necrosis factor-α (TNF-α), interleukin-1β (IL-1β), and interleukin-6 (IL-6), which leads to disruption of homeostasis and immune system disorders." (PMID 34504137, 2021). "Furthermore, we found that levels of salivary IL-6, IFN-γ, IL-10, IL-17A, and TNF-α in OLP patients were significantly upregulated, likely because of the oral immune disorder." (PMID 28400582, 2017). "Some proinflammatory cytokines, such as interleukin-1β (IL-1β), interleukin-6 (IL-6), interleukin-8 (IL-8), and tumor necrosis factor α (TNF-α), which usually are termed as ‘bad guys’, are reported to correlate with inflammation response and immune regulation as well as several immune diseases." (PMID 24718556, 2014). "Some IRPs in cluster 7, such as CXCL11, CXCL9, TNF, CXCL10, and IL18, are closely associated with HIV-1 disease progression and immune disorders, irrespective of whether patients received ART treatment." (PMID 36408648, 2023). "Altogether, our data indicate elevated contents of inflammatory cytokines TNF-α, IL-4, IL-21, BAFF, IL-31, IL-5 and APRIL in CSF samples from ASD patients, suggesting the potential inflammatory conditions and immune dysfunctions that might contribute the pathogenesis and progression of this disease." (PMID 38114596, 2023). "Although DN has not been considered to be an immune disease, inflammation (characterized by elevation of various inflammatory factors, including interleukin (IL)-6 and tumor necrosis factor-alpha (TNFα)) has been proved to participate in the pathogenesis of DN." (PMID 35350980, 2022). "In addition, it has been suggested that EBV stimulates T lymphocytes, releasing a variety of cytokines such as TNF, interferon (IFN), and interleukin-1 (IL-1), which may lead to immune dysfunction." (PMID 26108796, 2015). "The reason for this situation may be the presence of immune dysfunction in MDD patients, and low levels of IFN-α have the immunomodulatory function of activating monocytes and/or macrophages to enhance the production of various cytokines (e.g., TNF-α, IL-1, IL-6, etc.)by both." (PMID 39911552, 2024). "In addition, the factors of sex, immunodeficiency (such as glucocorticoid therapy, HIV-infected immunosuppression, or tumor necrosis factor antagonist therapy), different sites of MTB infection, smoking, diabetes, etc., may have effects on false-negative or uncertain QFT-GIT results." (PMID 36288019, 2022). "The suppression of TNF-α-induced NF-κΒ activation that was not accompanied by the activation of GR transcriptional activation may possibly indicate essential oils’ potential applications to the treatment of immune system disorders, minimizing the adverse side effects of glucocorticoids." (PMID 37511910, 2023). "The increased amount of CD4+CD28− T lymphocytes in patients with MHE indicates stronger immune dysfunctions than in patients without MHE, with persistent immune activation, increased production of TNFα, IFNγ and of molecules which may damage endothelial cells and tissues." (PMID 28751644, 2017).
infectious disease (237 papers, 2006 to 2026). A disorder directly resulting from the presence and activity of a microbial, viral, or parasitic agent in humans. "Deficiencies in crucial cytokines, such as IL-6, IL-1β, and TNF-α, have been linked to severe infectious diseases." (PMID 38213288, 2024). "Multifunctional T cells expressing a variety of cytokines (IFN-γ, TNF-α, IL-17, and IL-2) are associated with host protection against infectious diseases." (PMID 38932351, 2024). "It is well known that anti-TNF-α agents increase the risk of re-activation or triggering of infectious diseases compared with anti-interleukin agents." (PMID 37764964, 2023). "Previous studies have shown an increased risk for overall infectious diseases during treatment with IM or anti-TNF." (PMID 35140875, 2022). "As of January 2022, immunosuppressants such as tumor necrosis factor inhibitors (anti-TNFα) and azathioprine are inadvisable for an infectious disease caused by the SARS-CoV-2 virus (COVID-19)." (PMID 35089243, 2022). "Increased TNF-α production is linked to two biallelic polymorphisms in TNF-α, one associated with severe infectious diseases." (PMID 37521843, 2022). "IBD treatments including TNF-α inhibitors, corticosteroids and immunomodulators alter the immune system, leading to an increased risk for an infectious disease." (PMID 35268450, 2022). "Mediators of changes in thyroid function during acute and chronic illnesses are much varied, but pro-inflammatory cytokines including IL-1, IL-6 and TNF-α have been implicated in several infectious diseases." (PMID 34650659, 2021). "The components of innate immunity, such as natural killer cells, complement proteins, macrophages, dendritic cells and tumor necrosis factor alpha, cause a rapid and intense protection for the acute phase of infectious diseases." (PMID 32751625, 2020). "TNF-α has both a beneficial and deleterious role and it has been linked with infectious diseases and autoimmune disorders." (PMID 31409832, 2019). "A number of single nucleotide polymorphisms (SNPs), which are thought to affect the TNF-α production, have been found to alter individual susceptibility to a wide spectrum of infectious disease." (PMID 29939989, 2018). "TNF-α has been putatively implicated in the pathogenesis of a variety of diseases including infectious disease, autoimmune disorders, neoplasia, and malignant diseases." (PMID 29939989, 2018). "A number of single nucleotidepolymorphisms have been discovered in the TNF-α locus andhave shown to influence the rate of transcription and protein production ofTNF and their association with various infectious diseases." (PMID 28935761, 2017). "Sustained high levels of IL-10, and in particular sustained high IL-10/TNF ratio have been demonstrated to be associated with high mortality in meningococcal sepsis as well as in other infectious diseases." (PMID 28261486, 2017). "TNF-α is a potent immunomodulator and proinflammatory cytokine that has been implicated in the pathogenesis of autoimmune and infectious diseases." (PMID 24358317, 2013). "It is possible that DON exposure resulting in decreased levels of TNF-α contributes to impairment of immune function in poultry and increased susceptibility to infectious diseases when birds are fed DON for long periods." (PMID 23977054, 2013). "Some investigators have shown that TNF-α genotypes do influence the severity of infectious diseases, while others have concluded that polymorphisms of this gene promoter are of no functional consequence." (PMID 23267696, 2012). "The most studied SNP is at position −308 (rs1800629), with the A allele associated with 20%–40% greater TNF production and with susceptibility to and severity of numerous infectious diseases." (PMID 22172537, 2011). "In the past numerous studies have been performed to investigate the association of TNFA promoter polymorphisms and TNF-α levels in different inflammatory and infectious diseases, reporting contradictory results." (PMID 21385363, 2011).
infectious disease (continued). "The leukocyte specific transcript-1 is a gene with extensive alternative splicing and is encoded within the TNF region of the HLA complex, and plays a role in inflammatory and infectious diseases." (PMID 20668555, 2010). "Since TNF promoter SNPs were first described, multiple laboratories have studied their association with susceptibility to autoimmune and infectious diseases." (PMID 17637837, 2007). "KEGG enrichment analysis involves infectious diseases caused by many pathogens, including the TNF signaling pathway, the HIF-1 signaling pathway, the Toll-like receptor signaling pathway, the apoptosis signaling pathway, the PI3K/AKT signaling pathway, and the NF-κB signaling pathway." (PMID 35287352, 2022). "Additionally blocking of TNF signaling increases the risk for the development of infectious disease, since TNF is an important driver in pathogen clearance as well." (PMID 33435303, 2021). "Taken together, an important consideration is that environmental contaminants that impact TNF expression may influence infectious disease susceptibility." (PMID 25479081, 2014). "It is well known that TNFα plays a crucial role in autoimmune and infectious diseases as a proinflammatory cytokine; however, the mechanism of altered PsV & PsA risk owing to SNPs in the TNFα gene promoter region remains unknown." (PMID 23717605, 2013). "Interestingly, our analysis identified the hallmark pathways of TNF alpha signalling via NF-κB, the inflammatory response, innate and adaptive immune systems, infectious disease and processes, such as neutrophil degranulation and cytokine signalling, among those significantly enriched in LS10." (PMID 36979123, 2023). "However, TNF-α blockers increase the risk of infectious diseases." (PMID 34158982, 2021). "On the other hand, this interception of inflammatory cytokines such as TNF-α, which are direct factors in the creation of inflammation, may restrain protective physiological reactions and cause reactions that can revive infectious diseases such as TB that are in dormancy." (PMID 25317081, 2014). "Further visceral adipose tissue produces more cytokines including tumor necrosis factor α and interleukin 6 and 1β, which weaken the immune response against infectious diseases." (PMID 41003144, 2025). "In infectious diseases, macrophages form the first line of defense by engulfing pathogens and releasing proinflammatory cytokines, such as TNF-α." (PMID 40356647, 2025). "Pesticide exposure suppresses fish immunity, adversely impacting cytokine gene expressions such as interleukin (IL)-1β, IL-8, and tumor necrosis factor (TNF)-α, making them vulnerable to infectious diseases." (PMID 38722391, 2024). "Future studies are now planned to determine if noninvasive vcMNG at the RNG site can be employed to detect the initial TNF-α rise and the subsequent decline and resolution in patients admitted with infectious disease." (PMID 39075164, 2024). "TNF is the earliest cytokine released by the body and is a candidate gene for serious infectious diseases." (PMID 38848433, 2024). "Alterations in the DNA sequence within regulatory regions can potentially alter transcriptional regulation, thereby affecting TNF levels in the bloodstream and augmenting vulnerability to various infectious diseases." (PMID 39301021, 2024). "TNFα and IL-1β are the most important mediators of inflammation by gram-positive bacteria during infectious disease." (PMID 38234660, 2024). "Th22 cells, known to promote neutrophil mobilization and activation through cytokine secretion (IL-22 and TNF-α), play a crucial regulatory role in autoimmune and infectious diseases." (PMID 39039547, 2024). "Infectious diseases are identified by triggering inflammatory genes such as nuclear factor kappa B (NF‐kB) that in turn activates IL‐6 and TNF‐α." (PMID 37025056, 2023).